NWD2 (NACHT and WD repeat domain containing 2)
Synonyms: KIAA1239
Tractability: PROTAC: ubiquitination databases record sites on it; its protein half-life has been measured.
Gene: Protein-coding gene on chromosome 4 (37,244,743 to 37,449,463, forward strand). Ensembl gene ENSG00000174145.
Gene Ontology:
Cellular component: synapse
Genetic constraint (gnomAD): Loss-of-function variants: 28 observed, 119.03 expected, observed/expected ratio (o/e) 0.24, 90% interval 0.17 to 0.32. The synonymous counts are far from expectation, so gnomAD's model fits this gene poorly and the ratio says little. Missense variants: 1,524 observed, 2,095.8 expected, observed/expected ratio (o/e) 0.73, 90% interval 0.7 to 0.76. Synonymous variants: 674 observed, 804.06 expected, observed/expected ratio (o/e) 0.84, 90% interval 0.79 to 0.89.
Homologues: Orthologues: chimpanzee NWD2 (99% identical), macaque NWD2 (99% identical), dog NWD2 (96% identical), rabbit NWD2 (96% identical), pig NWD2 (95% identical), mouse Nwd2 (95% identical), rat Nwd2 (94% identical), guinea pig NWD2 (92% identical), tropical clawed frog nwd2 (78% identical), zebrafish nwd2 (72% identical), Caenorhabditis elegans Y111B2A.12 (4% identical), Drosophila melanogaster CG5114 (4% identical). Paralogues in human: AAMP (6% identical).
Diseases named in the same sentence as NWD2 in open-access papers:
NWD2 is named in the same sentence as 1 disease in open-access papers, as found by Europe PMC text mining. Sharing a sentence is not in itself a finding about the gene and the disease.
NWD2 shares sentences with these, for which no sentence is quoted: tumor (1 paper).